HLA-B (major histocompatibility complex, class I, B)
Diseases named in the same sentence as HLA-B in open-access papers (continued):
Sharing a sentence is not in itself a finding about the gene and the disease.
toxic epidermal necrolysis (continued). "It is interesting to note that the presence of an arginine at residue 62 in the HLA-B*1502 allele has recently demonstrated a role in carbamazepine-induced hypersensitivity producing Stevens-Johnson syndrome/toxic epidermal necrolysis." (PMID 23874514, 2013). "Stevens-Johnson syndrome (SJS) and Toxic Epidermal Necrolysis (TEN) are rare but extremely severe cutaneous adverse drug reactions in which drug-specific associations with HLA-B alleles were described." (PMID 21801394, 2011). "However, it is necessary for patients to perform a PGx testing before using these drugs, for the severe adverse reactions maculopapular exanthem, Stevens-Johnson syndrome and toxic epidermal necrolysis are all related to Human leukocyte antigen B (HLA-B) genotype polymorphism." (PMID 36937844, 2023). "Stevens-Johnson syndrome (SJS) and Toxic Epidermal Necrolysis (TEN), caused by allopurinol therapy, are strongly associated with the human leukocyte antigen (HLA), HLA-B*5801." (PMID 24732692, 2014). "HLA-B*15:02 is associated with Stevens-Johnson syndrome (SJS) and toxic epidermal necrolysis (TEN) induced by carbamazepine, oxcarbazepine and phenytoin, and lamotrigine." (PMID 40873549, 2025). "For example, in Asian populations, HLA-B*1502 was identified as a strong genetic risk factor for carbamazepine-induced Stevens–Johnson syndrome (SJS) and toxic epidermal necrolysis (TEN)." (PMID 38137494, 2023). "The HLA-B*58:01 allele is considered a biomarker of severe CAR (SCAR) in patients with gout, with symptoms of Stevens Johnson syndrome, and with toxic epidermal necrolysis." (PMID 34573954, 2021). "One prominent report on drug-induced SCARs is the association between HLA-B*15:02 allele and carbamazepine (CBZ)-induced Stevens–Johnson syndrome/toxic epidermal necrolysis (SJS/TEN) in Han Chinese, Thai, and Southeast Asians." (PMID 32180714, 2020). "Strong association between HLA-B*58:01 and allopurinol-induced severe cutaneous adverse reactions such as Stevens–Johnson syndrome (SJS) or toxic epidermal necrolysis (TEN) have been reported across different populations." (PMID 29760718, 2018). "For instance, some variants in the HLA-B*1502 allele are related to carbamazepine-induced Stevens-Johnson syndrome (SJS) and toxic epidermal necrolysis (TEN), which are severe disorders of the skin and mucosal membranes." (PMID 32467882, 2018). "There has been a strong association reported between the HLA-B*1502 haplotype and the severe life-threatening cutaneous drug reactions, Stevens-Johnson syndrome (SJS) and toxic epidermal necrolysis (TEN)." (PMID 24885933, 2014). "The HLA-B*15:02 allele is strongly associated with carbamazepine (CBZ)-induced Stevens-Johnson syndrome (SJS) and toxic epidermal necrolysis (TEN), therefore, the United States Food and Drug Administration (FDA) in 2007 recommended performing a pharmacogenomic test before starting drug treatment." (PMID 40873549, 2025). "The association with HLA‐A*31:01 in patients with SCAR was mainly driven by hypersensitivity syndrome (OR = 12.9; P = 2.1 × 10−9) rather than by Stevens‐Johnson syndrome/toxic epidermal necrolysis cases, which showed an association with HLA‐B*57:01." (PMID 31066027, 2019). "The HLA-B*15:02 allele is known as the most significant human leukocyte antigen marker associated with carbamazepine (CBZ)-induced Stevens-Johnson syndrome and toxic epidermal necrolysis in various Asian populations." (PMID 27196420, 2016). "The FDA added a Boxed Warning to its prescribing information requiring pre-treatment genetic testing in certain populations for HLA-B*15:02 due to Stevens-Johnson syndrome/Toxic Epidermal Necrolysis (SJS/TEN) risks." (PMID 36588876, 2022). "In Thais, there has been a well-documented association between HLA-B*15:02 and CBZ-induced Stevens-Johnson syndrome (SJS) and toxic epidermal necrolysis (TEN)." (PMID 35865943, 2022).
toxic epidermal necrolysis (continued). "Carriers of the human leukocyte antigen HLA-B*15:02 allele who are of Asian descent are at an increased risk of developing Stevens-Johnson syndrome (SJS) and toxic epidermal necrolysis (TEN)." (PMID 34440433, 2021). "In patients with the HLA-B*1502 allele, antiepileptic drugs with an aromatic ring in their structure, i.e., carbamazepine, oxcarbazepine, lamotrigine and phenytoin, have been shown to cause Stevens–Johnson syndrome (SJS) or toxic epidermal necrolysis (Lyell’s syndrome, LS)." (PMID 34769124, 2021). "For example, the HLA-B*1502 allele is connected with an increased risk of developing Stevens-Johnson syndrome (SJS) and its related disease, toxic epidermal necrolysis (TEN) during carbamazepine or oxcarbazepine treatment." (PMID 32226396, 2020). "Indeed, various HLA specific alleles have been demonstrated to be directly involved in drug toxicities, such as HLA-B*57:01 with the abacavir-induced hypersensitivity reaction, HLA-B*15:02 with carbamazepine-induced Stevens–Johnson syndrome, and toxic epidermal necrolysis with high test sensitivity." (PMID 29298994, 2019). "For instance, carbamazepine (brand name Tegretol) is used for the treatment of seizures, but patients carrying the HLA-B*15:02 variant have an increased likelihood to suffer from the Steven-Johnson Syndrome (SJS) or toxic epidermal necrolysis (TEN)." (PMID 28303164, 2017). "Despite some studies suggesting a possible association between human leukocyte antigen, HLA-B*5801 and allopurinol induced Stevens-Johnson Syndrome (SJS) and Toxic Epidermal Necrolysis (TEN), the evidence of association and its magnitude remain inconclusive." (PMID 21906289, 2011). "HLA-B*15:02 is associated with Stevens–Johnson syndrome (SJS) and toxic epidermal necrolysis (TEN), while HLA-A*31:01 is linked to an increased risk of drug reaction with eosinophilia and systemic symptoms (DRESS), as well as SJS/TEN induced by aromatic antiepileptic drugs." (PMID 41471361, 2025). "Studies have identified HLA-B as a key genetic factor in ADRs, particularly severe cutaneous adverse reactions (SCARs) such as Stevens-Johnson syndrome (SJS), toxic epidermal necrolysis (TEN), and drug rash with eosinophilia and systemic symptoms (DRESS)." (PMID 39464636, 2024). "HLA-B*44:03: serious allergic reaction of skin and mucosa with complex pathogenesis including SJS and toxic epidermal necrolysis (TEN) is considered to be a non-immediate hypersensitivity reaction mediated by T cells." (PMID 34973118, 2022).
HIV-1 infection (60 papers, 2006 to 2024). The type species of lentivirus and the etiologic agent of acquired immunodeficiency syndrome (AIDS). "NK cells with at least one copy of the KIR3DS1 gene exhibited enhanced degranulation and IFN-γ responses in acute phase HIV-1 infection, in particular in individuals also encoding for HLA-B*57 and B*58." (PMID 39459918, 2024). "Detrimental HLA allele associations have also been reported; in HIV-1 infection, a subset of HLA-B*35 alleles, HLA-B*35Px, is associated with high setpoint viral load and faster progression to disease." (PMID 36719466, 2023). "To illustrate this, we compared binding preferences of HLA-B*57:01, associated with a good disease prognosis in HIV-1 infection, and HLA-B*08:01, associated with a poor prognosis." (PMID 36605212, 2022). "The dimorphism at position -21 of HLA-B (M/M genotype) has been associated with increased susceptibility to HIV-1 infection." (PMID 32132995, 2020). "CTLs play a major role in the protective effects of HLA-B*57 and HLA-B*27 in early HIV-1 infection and CTLs restricted by these alleles better define disease progression than HLA-genotype alone." (PMID 28769934, 2017). "The role of HLA-A allele group in HIV-1 infection is less appreciated than HLA-B alleles, possibly due to observed differences in their CTLs function." (PMID 28769934, 2017). "Since U397 cells are susceptible to HIV-1 infection and express HLA-B*2705, we can rapidly evaluate HIV-1 infectivity and CD8+ T-cell inhibition." (PMID 27440884, 2016). "Association of particular HLA-B alleles with HIV-1 infection outcomes is traditionally linked to the ability of the corresponding allotypes to elicit CTL responses." (PMID 24603468, 2014). "Expression of HLA-B*57 and the closely related HLA-B*58:01 are associated with prolonged survival after HIV-1 infection." (PMID 24339913, 2013). "This study sought to determine the role of HLA-B alleles in viral control during the acute phase of HIV-1 infection and establishment of the early viral load set point (VLSP)." (PMID 24245727, 2013). "HLA-B alleles are associated with viral control in chronic HIV-1 infection, however, their role in primary HIV-1 disease is unclear." (PMID 24245727, 2013). "Taken together, our data demonstrate that amino acid polymorphisms at position 97 of HLA-B are broadly associated with viral control during primary HIV-1 infection, while HLA-B*57 has a later effect which is more pronounced at the time of the early VLSP." (PMID 24245727, 2013). "We then investigated the protective effect of known HLA-B alleles during the course of primary HIV-1 infection." (PMID 24245727, 2013). "Protective HLA class I alleles (HLA-B*27 and B*57) have been consistently found to be overrepresented in cohorts of HICs who spontaneously control HIV-1 infection." (PMID 23516360, 2013). "The effect of HLA-B*57 on viral control is more pronounced during the later stages of primary HIV-1 infection, which suggests the underlying mechanism of control occurs at a critical period in the first several months after HIV-1 acquisition." (PMID 24245727, 2013). "The HLA-B*35-Px allele has been associated with rapid disease progression in HIV-1 infection, in contrast to the HLA-B*35-Py allele." (PMID 20422053, 2010). "Finally, in HIV-1 infection, both the protective HLA-B*57 and detrimental HLA-B*35Px associations were enhanced in individuals with a high iKIR score; this was replicated in two independent cohorts." (PMID 36719466, 2023). "Targeting of the Rev-RI8 epitope in Rev by CTL could contribute to the positive association of HLA-B*52 with a more favorable course of HIV-1-infection." (PMID 36851781, 2023). "Consider, for example, HLA-B*57-associated protection in the context of HIV-1 infection." (PMID 32238263, 2020). "Residue 97 is spatially close to residue 116 (and they could therefore interact), and, in HLA-B, 97 is the residue most significantly associated with host control of HIV-1 infection." (PMID 26020813, 2015).
HIV-1 infection (continued). "We propose that the −237A variant could represent a minor causal SNP that additionally contributes to the HLA-B*5701-mediated ‘protective’ effect during HIV-1 infection." (PMID 22808100, 2012). "Besides the type of targeted viral protein and epitope, HLA-B restriction in general and HLA-B*5701 and B*2705 in particular have been associated with better control of HIV-1 infection." (PMID 21483676, 2011). "Supporting this hypothesis, residues 62–74 of Patr-B*06:03 and other members of the trans-species clade include four (62, 63, 67, and 70) of seven residues found by genome-wide association study (GWAS) to be most significant for HLA-B mediated control of HIV-1 infection." (PMID 26020813, 2015). "10-8) with elite control of HIV-1 infection, including well-established MHC signals such as the rs2395029-G allele which tags HLA-B*57:01." (PMID 38146367, 2023). "Individuals carrying HLA-B*14:02 control HIV-1 infection is related to an immunodominant Env-CD8 + T-cell response." (PMID 35346235, 2022). "Control of HIV-1 infection in LTNPs viremic controllers, have been associated with effective immunodominant HIV-1 Gag-CD8 + T-cell responses restricted by protective HLA-B alleles." (PMID 35346235, 2022). "We investigated the association of HLA-B, HLA-C, and KIR genotypes with TB, HIV-1 infection, and IRIS onset." (PMID 31959123, 2020). "Assessment of the overall impact of HLA-B dimorphism on the acquisition of or control of HIV-1 infection will need to take into account a number of effects in addition to the contribution of HLA/peptide complex availability and its impact on the NKG2 pathway." (PMID 32132995, 2020). "Molecules of HLA-B*27 and -B*57 have also been shown to give a protective effect in HIV-1 infection." (PMID 28332079, 2017). "In acute human HIV-1 infection, there is a rapid NK cell proliferation, in which the expansion of particular NK cell subsets depends upon the presence of Bw4-bearing HLA-B allotypes." (PMID 26020813, 2015). "Based on the work presented herein, we propose that variation in binding properties of HLA-B to the inhibitory myelomonocytic receptor LILRB2 can contribute to the overall HLA effects on HIV-1 infection outcomes." (PMID 24603468, 2014). "A correlation between the number of HLA-B*57 Gag epitopes and the level of viremia was observed in a cohort of HLA-B*5703 positive patients with Clade C HIV-1 infection." (PMID 24330837, 2013). "Recent cohort studies have demonstrated that particularly those individuals equipped with HLA-B*27 and/or -B*57 are able to control an HIV-1 infection." (PMID 23705941, 2013). "Natural control of HIV-1 infection is associated with T-cell responses against HIV-1 Gag proteins, particularly CD8+ T-cell responses restricted by “protective” HLA-B alleles, but other immune responses also contribute to immune control." (PMID 26344116, 2013). "We here studied whether the variation in clinical course of HIV-1 infection of HLA-B*57/58:01-positive individuals may be explained by differences in the number of mutations that restore fitness of viral variants that escaped from HLA-B*57/58:01-restricted CTL pressure." (PMID 24339913, 2013). "Further, KIR3DS1+ NK cells selectively expand during acute HIV-1 infection in the presence of HLA-B Bw4-80Ile." (PMID 22194686, 2011). "Immune responses to two HLA-B*35 restricted HIV-1 specific CTL epitopes and their variants were followed longitudinally during early HIV-1 infection in 16 HLA-B*35+ individuals." (PMID 20422053, 2010). "Additionally, co-carriage of the KIR3DL1 homozygous genotype (KIR3DL1*h/*y) together with HLA-B*57 was more frequent in HESN individuals compared to persons with acute HIV-1 infection (AHI)." (PMID 39459918, 2024). "HLA-B*44 and -B*51 have not consistently been shown to play a protective role in HIV-1 infection, and the HLA-B*05, -B*13, -B*17, -B*37, and -B*38 alleles and some other non-protective HLA antigens, also express the Bw4 public motif." (PMID 30147699, 2018).
HIV-1 infection (continued). "For example, HLA-B*6701 and HLA-B*5201-C*1202 haplotypes are protective alleles found in Japanese individuals with HIV infection, CTLs restricted by these alleles control HIV-1 infection progress." (PMID 30534128, 2018). "This hypothesis would be in line with the protective effect exerted by the combined presence of KIR3DS1 and HLA-B Bw4-I80 in patients with chronic HIV-1 infection." (PMID 28603523, 2017). "HLA-B*57 allele is associated with long-term non-progressive chronic HIV-1 infection by restricting cytotoxic T-lymphocyte response." (PMID 28289388, 2017). "While HLA-C allotypes also show fairly broad variation in binding scores similar to HLA-B, their lower expression levels may diminish their effect in regulating myelomonocytic cells in HIV-1 infection." (PMID 24603468, 2014). "The results showed that neither HLA-B*57 nor HLA-B*27 were significantly associated with viral control during acute HIV-1 infection (Fiebig stage I-IV, n=171)." (PMID 24245727, 2013). "Of note, the capacity of CD8+ T cells from the PTCs to suppress HIV-1 infection was still weaker than that of the subset of HICs that did not bear the HLA-B*27 or B*57 alleles (1.55 [0.71–3.28], p = 0.002, n = 29)." (PMID 23516360, 2013). "It will be crucial to confirm these findings in larger cohorts with more viral load measurements to determine if HLA-B*57 may have a weaker than 1 log10 effect during acute HIV-1 infection." (PMID 24245727, 2013). "Thus, the major effect of HLA-B*57 on viral replication occurs later in primary HIV-1 infection at the time of the early VLSP, while the protective effect for HLA-B27 has been suggested to occur even later." (PMID 24245727, 2013). "We particularly investigated whether monocytes are infected in vivo and tested the hypothesis of a limited infection of TCM, like in non-pathogenic SIVsm infection or in the non-progressive HIV-1 infection of HLA-B*27+ or B*57+ LTNPs." (PMID 31095640, 2019). "This raises the question of whether higher polyfunctionality, more avidity and greater clonal expansion of HLA-B restricted alleles could be in part due to HIV Nef evasion in these individuals or other factors enabling HLA-B restricted CTLs confer better protection against HIV-1 infection." (PMID 28769934, 2017). "HLA-B*57 was first described as associated with a long-term non-progressive phenotype in chronic HIV-1 infection in 1996, yet a clear understanding of how and why this allele contributes to the host response against viral replication still remains largely elusive." (PMID 24245727, 2013). "Currently, the role of HLA-B alleles in primary HIV-1 infection is not well described." (PMID 24245727, 2013). "The most commonly targeted epitope during early HIV-1 infection was SAAVKAACW (IN 123–131), located in IN, and possibly presented by HLA-B*58:01." (PMID 35346259, 2022). "In addition, HLA-B genotypes HLA-B57/B58 or -B27, HLA-B*35:01 and HLA-C, such as the HLA-C*03:02 1 in an African Pediatric Population, are linked with the control of HIV-1 infection (non-progressors bottom box)." (PMID 36140273, 2022). "It would seem likely that NK cells would be skewed toward killing infected cells since HIV-1 infection leads to increased expression of ICAMs on the infected cell surface, induces expression of ULBP-1 and ULBP-2, and down modulates HLA-A and HLA-B." (PMID 21994772, 2011). "Since a continuous high viral load is seen during chronic HIV-1 infection, persistent exposure to HIV-1 antigens may compensate for the small amount of antigen presentation due to weak binding of MI8 epitope peptide to HLA-B*52:01." (PMID 34076478, 2021). "We report that the protective effect of HLA-B*57 is more pronounced later in primary HIV-1 infection rather than during the acute phase." (PMID 24245727, 2013). "Individuals with HLA-B*57 have been shown to have milder or absent symptoms during acute HIV-1 infection, which led us to question if this molecule might play a role through early innate mechanisms." (PMID 24245727, 2013).
HIV-1 infection (continued). "However, HLA-B*3501-mediated protection from HIV-1 infection is not uniquely due to lower-affinity binding to ILT4, and may also be a result of the altered breadth of the CD8+ T cell response." (PMID 30534128, 2018). "Moreover, in the same group, the association between HIV-1 p24-specific IgG Abs and natural control of HIV-1 infection in individuals not carrying HLA-B*5701 was only observed in HIV controllers, but not in elite controllers or non-controllers (>10,000 copies/mL)." (PMID 30534128, 2018). "Approximately one third of HIV-1 controllers do not exhibit evidence of HLA-B-restricted CD8+ T-cell responses against Gag proteins, suggesting that other immune responses also contribute to natural control of HIV-1 infection." (PMID 26344116, 2013).